KRAS (KRas proto-oncogene, GTPase)
Diseases named in the same sentence as KRAS in open-access papers (continued):
Sharing a sentence is not in itself a finding about the gene and the disease.
lymph node metastasis (75 papers, 2009 to 2025). "Its potential in predicting lymph node metastasis, as well as gene mutations such as KRAS, NRAS, and BRAF has been evaluated." (PMID 41295561, 2025). "KRAS mutations were detected in 8/17 samples (47.1%) of locally advanced cancer, 4/12 samples (33.3%) of peritoneal or lymph node metastasis, and 14/17 samples (82.3%) of liver or lung metastasis." (PMID 36810451, 2023). "In the multivariable analysis; independent predictors of poor OS were KRAS mutation (HR = 5.384; p = 0.003) and lymph node metastases (HR = 2.805; p = 0.023)." (PMID 36139531, 2022). "ITGB1 expression was associated with lymph node metastasis, expression of integrin alphaV and KRAS mutation status." (PMID 36456612, 2022). "Regarding KRAS status in ctDNA, cases with preoperative KRAS mutation positive for ctDNA tended to have lymph node metastasis and distant metastasis." (PMID 33432066, 2021). "Expression of EGFR > 35% was associated with the presence of lymph node metastases (p = 0.001), liver metastases at diagnosis (p < 0.001), advanced stages of the disease (p < 0.001) and KRAS mutations (p = 0.001)." (PMID 32170146, 2020). "KRAS exon 2 mutation appeared more frequent in older patients (average age: 67.7 years old vs 64.9 years old; P = 0.036) and was associated with higher lymph node metastasis rate (52.3% vs 41.6%; P = 0.046)." (PMID 29666387, 2018). "And found KRAS exon 2 mutations occurred more frequently in older patients and patients with lymph-node metastases." (PMID 29666387, 2018). "All ACs were derived from patients who did not receive any preoperative or postoperative treatment and were classified according to the tumor grade, lymph node metastasis, and the KRAS and EGFR mutational status." (PMID 28860622, 2017). "In patient 1, tumour 3 (and the associated lymph node metastasis) harboured a KRAS p.G12V mutation, whereas tumour 1 had a KRAS p.G12A mutation." (PMID 27767028, 2016). "In patient 1, tumour 3 (T3) and a lymph node metastasis shared 52 (26%) of 198 mutations, including a KRAS (p.G12V) mutation and a STAG2 nonsense mutation (p.R305X), suggesting that the tumour metastasized to the lymph node." (PMID 27767028, 2016). "A significant association was found between the presence of lymph node metastases and pMMR tumors stratified by KRAS mutation status." (PMID 26042813, 2015). "In one patient, two lymph node metastases were found that harbored two different KRAS mutations, which corresponded with that of the IL and CL, respectively." (PMID 24765171, 2014). "Overexpression of EGFR and KRAS proteins was associated with lymph node metastasis and with a more advanced pathologic stage." (PMID 22537942, 2012). "The reduced expression of RBM5 protein was associated with tobacco smoke, tumor stages, and lymph node metastasis of NSCLC, while overexpression of EGFR and KRAS proteins was associated with tumor stages and lymph node metastasis of NSCLC." (PMID 22537942, 2012). "Discordance in KRAS mutation status between primary tumors and lymph node metastases observed in six patients was found statistically significant (McNemar's test, P = 0.0412)." (PMID 21414214, 2011). "Moreover, in the multivariable analysis, KRAS mutation together with lymph node metastases were the strongest predictors of poor OS." (PMID 36139531, 2022). "In addition, the status of lymph node metastasis was also an independent risk factor for the prognosis of patients with KRAS mutations (HR 2.274, 95% CI, 1.028–5.031 log‐rank test, p < 0.05)." (PMID 35686701, 2022). "Also, amplification of KRAS was previously found to be significantly associated with lymph node metastasis and poor OS in OAC patients treated with upfront resection." (PMID 33506581, 2021).
lymph node metastasis (continued). "In particular, KRAS codon 12 mutated carcinomas had increased lymph node metastasis (odds ratio [OR] = 1.31; 95% confidence interval [CI] = 1.04 to 1.65; P = 0.02) and were more likely in higher disease stage (III-IV) than that of WT carcinomas (OR = 1.30; 95% CI = 1.03 to 1.64; P = 0.03)." (PMID 25929517, 2015). "In one patient, lymph node metastasis was found harboring the same KRAS mutation as that in the CL." (PMID 24765171, 2014). "Discordance in KRAS mutation status might be due to clonal selection during the process of metastasis, however, heterogeneity in lymph node metastases could explain this discordance in only one patient." (PMID 21364579, 2011). "Comprehensive analysis indicated that the expression of LINC01600 was significantly associated with KRAS mutation and lymph node metastasis, and CASC15 and LINC01600 were significantly tended towards co-occurrence, which may be due to the similarity of genes co-expressed by these 2 lncRNAs." (PMID 37960753, 2023). "One case showed a different major genetic alteration (KRAS mutation) since day 0, which was probably due to the heterogeneity of the parental tumour causing sampling bias, although we were unable to trace back the genetic alteration in the patient matched-parental tumour or lymph node metastasis." (PMID 34572922, 2021). "Considering the decreased proportion of lymph node metastasis in mutated KRAS patients compared to wtKRAS subgroup, it seems that carcinoma cells with activating mutation in KRAS may exhibit a more hematogenous metastatic spread rather than along a lymphogenous path." (PMID 25888291, 2015). "All CTCs harbouring KRAS mutations were from patients with advanced pathological stages (III or IV) and with lymph node metastasis." (PMID 37761948, 2023). "Recently, KRAS has been prominently noticed in the field of head and neck cancer research due to its strong relationship with tumorigenesis, invasion, lymph node metastasis, recurrence, and prognosis." (PMID 36532636, 2022). "While, lymph node metastasis (P = 0.02) and LNR (P <0:001) rate was significantly higher in KRAS codon 12 mutated tumors." (PMID 33784337, 2021). "Subsequently, we investigated the relationship between KRAS status in ctDNA and lymph node metastasis and with distant metastasis." (PMID 33432066, 2021). "We consider the alternative that KRAS amplification only manifest itself in the course of lymph node metastasis to be unlikely." (PMID 32571252, 2020). "In contrast to RBM5, overexpression of KRAS was significantly correlated with tumor size, lymph node metastasis, UICC stage and nerve invasion (P<0.05)." (PMID 23425895, 2013). "Patients with KRAS mutations exhibited a higher rate of overall distant organ metastasis (70.3%), including metastasis to the liver (44.1%) and lungs (19.8%), whereas patients with BRAF mutations showed a higher rate of lymph node metastasis (82.4%)." (PMID 40075837, 2025). "Therefore, the study concluded that KRAS mutation, TBS, TMS, and primary lymph node metastases were independent prognostic indicators for patients with CRLM." (PMID 38698687, 2024). "In addition, the same study showed that PD-L1 expression was also associated with male gender, smoke, lymph node metastasis, EGFR wild-type status, KRAS mutations, and overall survival." (PMID 33155793, 2021). "There was no significant age, gender, histologic type, tumor size, lymph node metastasis, tumor focality, and surgical margin status differences between KRAS mutated and non-mutated PTC." (PMID 32315324, 2020). "KRAS mutation rate was higher in patients with histologically well/moderate grade tumor (39.4% vs 25.7%, P=.02) or in patients without distant lymph node metastasis (40.8% vs 28.9%, P=.05)." (PMID 27050078, 2016).
lymph node metastasis (continued). "Most importantly, patients with KRAS(+)/pMMR tumors showed increased lymph node metastasis among four subtypes and may have worse survival rate." (PMID 26042813, 2015). "The lymph node metastasis KRAS genotype corresponded with that of the IL in 12 out of 14 patients." (PMID 24765171, 2014). "In univariate analysis, Grade 3, ECOG performance status 2, the presence of multiple metastatic sites, the presence of KRAS mutation, the presence of liver metastases, the presence of nonregional lymph node metastases, and the presence of bone metastases were significant predictors of poor survival." (PMID 38947890, 2024). "In addition, ACY1 expression levels were lower in patients with KRAS mutation but no lymph node metastasis (group B) than in group C. The expression levels were lowest in patients without lymph node metastasis and KRAS mutation (group A)." (PMID 36428796, 2022). "Due to the mutations of KRAS and EGFR in NSCLC are mutually exclusive, we divided our LUAD patients into WT and MT EGFR subgroups and found that the T allele of rs8193036 was only correlated with an advanced stage and lymph node metastasis in LUAD patients harboring the WT EGFR." (PMID 33802737, 2021). "Despite several meta-analysis studies exploring the role of 18F-FDG PET/CT in CRC, including the diagnosis of lymph node metastasis, KRAS mutation, and prognostic value, none analyzed the association of the SUVmax with KRAS mutation, the Ki-67 index, and their prognostic value." (PMID 34956868, 2021). "However, liver (37.3% vs. 70.6%; P < 0.001) or distant lymph node metastases (6.7% vs. 19.1%; P = 0.025) were less frequent as the initial metastatic organ in patients with the KRAS mutation than in patients without the KRAS mutation." (PMID 22876814, 2012). "Like KRAS, it is noted that CTLA-4 expression was also higher in patients with lymph node metastasis, advanced pathological stages (72.7% vs. 50.0%), and MSI-stable cancer (68.4% vs. 25.0%)." (PMID 37761948, 2023). "We also found that amplifications of KRAS and ERBB2 gene were present only in the lymph node metastasis and right middle lobe of P06, respectively." (PMID 34290355, 2022). "In conclusion, NeoRAS WT mCRC is associated with the absence of liver and lymph node metastases, as well as RAS MTs other than KRAS exon 2 MTs." (PMID 39003289, 2024). "KRAS status in ctDNA and lymph node metastasis and distant metastasis were not significantly different." (PMID 33432066, 2021). "Other clinicopathological features, such as sex, age, depth of invasion, lymph node metastasis or TNM stage, did not exhibit any association with KRAS mutations, which is consistent with a recent report of Chinese patients." (PMID 26691448, 2015). "This means that KRAS mutation analysis should be included in the prognostic stratification of patients resected for PHC, in order to select patients for adjuvant chemotherapy in case of good pathologic results, such as T1–T2 stage or absence of lymph node metastases." (PMID 36139531, 2022). "Significant relationships determined between KRAS exon 2 and mucinous morphology, PIK3CA and absence of perineural invasion, BRAF and tumor differentiation and localization, MSH3 and tumor diameter, and BRCA2 and absence of lymph node metastasis were findings that have contributed to the literature." (PMID 37737217, 2023).
myeloma (68 papers, 1995 to 2026). "Approximately 20% of multiple myeloma patients harbor KRAS mutations, leading to activation of the MEK/ERK pathway." (PMID 37705755, 2023). "Pre-clinical results for AZD4785, a new drug that functions as an antisense oligonucleotide that downregulates all KRAS isoforms, has shown inhibition of myeloma cell growth with KRAS mutations." (PMID 36900299, 2023). "We therefore systematically analyzed the clinicopathologic, cytogenetic, and molecular genetic features as well as OS in a large group of myeloma patients with KRAS/NRAS/BRAF mutations." (PMID 37212518, 2023). "In multiple myeloma, KRAS mutations are substitutions at codon 61 for which, to our knowledge, there is no clinically available specific inhibitor." (PMID 36900299, 2023). "Clinical and laboratory characteristics of patients with plasma cell myeloma according to KRAS/NRAS/BRAF mutation status." (PMID 37212518, 2023). "In this study, our goal is to assess the clinical implications of KRAS/NRAS/BRAF mutations in myeloma patients, as these mutations have potential implications for targeted therapy." (PMID 37212518, 2023). "Recently, a potent and selective antisense oligonucleotide AZD4785 has been chosen to target and downregulate all KRAS isoforms and demonstrated its ability to silence KRAS and to inhibit multiple myeloma-tumor-bearing KRAS mutations." (PMID 36012138, 2022). "G12Si-5 also inhibited the growth of KMS20, a patient-derived myeloma cell line with a homozygous KRAS p.G12S mutation, with an IC50 of 7.5 μM." (PMID 35864332, 2022). "It is likely that KRAS-mutated cells survived the selection pressure imposed by combined anti-myeloma therapy (at the level of residual disease) but, with the evolution of MM, were dominated by other more aggressive clones at the time of overt relapse." (PMID 35884979, 2022). "In multiple myeloma, however, activating KRAS and NRAS mutations produce distinct expression signatures, necessitating separate classifiers." (PMID 35761387, 2022). "Single agent trametinib found early success in isolated individuals, including one KRAS-mutated patient with multiply relapsed myeloma and extramedullary disease who attained an impressive response with single agent trametinib." (PMID 35127532, 2021). "Agents targeting the RAS/MAPK pathway are well-positioned for clinical investigation given the frequency of NRAS and KRAS mutations in multiple myeloma and early examples of single agent and combination activity." (PMID 35127532, 2021). "While anecdotal responses of MEK inhibitors have been noted in myeloma, this further confirms response of this agent in an independent cancer type driven by KRAS mutations." (PMID 33859342, 2021). "Mutation analysis revealed NRAS as the most commonly mutated gene (30%, 7/23) in myeloma patients followed by KRAS (26%, 6/23) and BRAF (22%, 5/23)." (PMID 27634910, 2016). "Thus, the application of a targeted gene sequencing panel in myeloma patients identified mutations in mitogen activated protein kinase (MAPK) pathway-related genes (KRAS, NRAS, and BRAF)." (PMID 27634910, 2016). "Multiple myeloma (MM) was characterized by frequent mutations in KRAS/NRAS/BRAF within the EGFR pathway that could induce resistance to EGFR inhibitors." (PMID 25894462, 2015).
myeloma (continued). "Notably, oncogenic mutations of KRAS or NRAS are a hallmark of multiple myeloma (MM)." (PMID 41542462, 2026). "The decrease in the prevalence of KRAS mutations observed in some samples derived from relapsed/refractory MM patients in our study indicates that these mutations did not provide the cells carrying them with a selection advantage over other myeloma cells during relapse." (PMID 35884979, 2022). "Activating point mutations in KRAS are among the most prevalent genetic alterations in cancer, with highest incidences specific for certain epithelial (e.g., lung, pancreatic, and colorectal) and hematological (e.g., acute myeloid leukemia and multiple myeloma) malignancies." (PMID 30833304, 2019). "Indeed, using a targeted sequencing approach to screen highly expressed tyrosine kinase and cytokine signaling genes in primary human patient myeloma, we previously identified mutations at codon 12 and 61 in N- and KRAS as being the only recurrent variation in our sample set." (PMID 23825691, 2013). "Others have shown that myeloma is driven by mutations in the RAS signaling pathway, and that KRAS/NRAS mutations are present in 20%–50% and 45%–80% of newly diagnosed and relapsed/refractory myeloma cases, respectively." (PMID 37212518, 2023). "Mutations in the RAS‐MAPK pathway, such as KRAS, NRAS, and BRAF, are known as high‐risk factors associated with poor prognosis in patients with various cancers, but studies in myeloma have yielded mixed results." (PMID 37212518, 2023). "The first evidence of RAS mutations in mature B cell malignancies date back to 1989, when Neri and colleagues identified KRAS and NRAS mutations in a subgroup of multiple myeloma cases." (PMID 35158933, 2022). "RAS pathway hyperactivation is a common molecular event in progressive myeloma, with almost 75% of drug-refractory myeloma patients harboring mutations in NRAS, KRAS, or BRAF2." (PMID 35739276, 2022). "Proteasome addiction is well documented for myeloma and TNBC cells, while more recently, a small proof-of-concept human trial showed that some lung adenocarcinoma cancer patients with the KRAS G12D mutation responded well to proteasome inhibitor therapy." (PMID 35088066, 2022). "Cobimetinib in combination with ixazomib and pomalidomide is also being further investigated in the MYDRUG umbrella protocol in NRAS, KRAS, and BRAF-mutated myeloma." (PMID 35127532, 2021). "While there is an option to add in steroids, two myeloma patients had received RO5126766 alone, of which one of them (carrying both NRAS and KRAS mutations) achieved a partial response." (PMID 32228485, 2020). "We used RPPAs to examine the phosphoproteome to identify key sensitising pathways in KRAS-mutant myeloma cell lines treated with trametinib and dexamethasone." (PMID 32228485, 2020). "In our cohort, 46 patients were treated with at least 1 cycle of anti-myeloma treatment and 20 of them had BRAF, KRAS and NRAS mutations." (PMID 32284750, 2020). "Collectively, the generated protein–protein interaction analysis indicated a significant correlation between the driver oncogenomic mutation KRAS and MAF1 and abnormal basal autophagy in myeloma PCs." (PMID 32085480, 2020). "In the present study, TAK-580 specifically inhibited the RAS-RAF-MEK-ERK pathway and significantly induced anti-myeloma effects and apoptosis in NRAS-mutated INA-6 and KRAS-mutated RPMI-8226 MM cell lines." (PMID 33216827, 2020). "Beyond well-known myeloma genes such as KRAS, NRAS, DIS3, and FAM46C5–8, several other interesting candidate genes emerged." (PMID 31444325, 2019). "In general, the importance of MAP kinase signaling in PC biology is suggested by the recurrent mutations of NRAS, KRAS, and BRAF in myeloma." (PMID 30642980, 2019).